CCR2 (C-C motif chemokine receptor 2)
Diseases named in the same sentence as CCR2 in open-access papers (continued):
Sharing a sentence is not in itself a finding about the gene and the disease.
asthma (23 papers, 2004 to 2026). "It is therefore predictable that in an OVA-induced asthma model, CCR2 deficiency (CCR2 KO) results in defective trafficking of CD11c+DCs loaded with antigens during maturation in the lung tissue, leading to weakened Th2 immunity." (PMID 32038501, 2020). "The up-regulated genes have been previously associated with asthma; hyper-reactivity and allergy (CCR2, HRH2, PTEN); lung development and apoptosis (CHRNA7, RTKN2); and immune function (GIMAP4, GIMAP7, KLRC3 and CD99)." (PMID 30971730, 2019). "Previous experimental asthma studies involving CCR2-deficient mice have used mice of mixed genetic backgrounds, whereas we used mice that had been backcrossed nine times to C57BL/6 and therefore have a more homogenous genetic background." (PMID 15377395, 2004). "Macrophages expressing CCR2 have been implicated in asthma pathogenesis due to their expansion after allergen challenge in human asthmatics and have been identified as potential precursors for intra-epithelial macrophages and alternatively-activated macrophages in mouse asthma models." (PMID 38444858, 2024). "Acupuncture significantly decreased the expression of these chemokines, indicating inhibition of CCR2-mediated CD11b+ DC accumulation in asthma." (PMID 40405264, 2025). "CCR2 expression on monocytes indicated a tendency toward more phagocytic monocytes in patients with asthma." (PMID 31700522, 2019). "The differential expression of CD16, CX3CR1 and CCR2 on monocyte subsets in peripheral blood indicates modulation of the inflammatory response and suggests a role for monocytes in asthma pathogenesis." (PMID 31700522, 2019). "CCR2+ T cells are known to be involved in the pathogenesis of severe asthma indicating that either the effector memory pool becomes reduced or CCR2+ effector memory cells are confined to other compartments within the body." (PMID 26953825, 2016). "In the non-classical CD14+CD16++ subset, the percentage of monocytes expressing CCR2 was significantly higher in the patients with mild (24 ± 3; p < 0.0001), moderate (16 ± 2.5; p = 0.009) and severe (18 ± 2.7; p = 0.002) asthma compared to healthy (9%) controls." (PMID 31700522, 2019). "This differential expression of CD16, CX3CR1 and CCR2 on the monocyte subsets in peripheral blood indicates that monocytes may modulate the inflammatory response in asthma." (PMID 31700522, 2019). "This is consistent with our finding that monocyte subsets have decreased CD16+ associated with increased asthma severity and the suggestion that monocytes newly released from the bone marrow have not fully reduced CCR2 and acquired CX3CR1 in addition to CD16." (PMID 31700522, 2019). "The analysis also suggested that it was the CCR2-G190A polymorphism rather than the CCR5Δ32 that was associated with protection against asthma as this protective association was independent of its co-association with CCR532." (PMID 20220260, 2010). "Conversely, CCR2 facilitates CD11b+ DC recruitment to inflamed lungs through interactions with CCL2 and CCL8, both of which are highly expressed in asthma." (PMID 40405264, 2025). "Studies to mechanistically understand biologics that target CCR2 and CXCR5 along with chronotherapeutic approaches will provide a new direction in the treatment of asthma." (PMID 37781650, 2023). "The most influential nodes (Fn1, Igf1, Ccl2, C3, Timp1, Cxcl12, Ccl4, Ccr2, Spp1, C3ar1, Cat, Cyp2e1, Muc5ac, Muc5b) were selected for further validation in the OVA-induced asthma and post-asthmatic fibrosis murine model." (PMID 35625754, 2022). "In conclusion, these observations confirm previous findings of increased CCL2 levels in asthma and suggest that ASM-derived CCL2-mediated activation of CCR2 promotes FC migration." (PMID 24931417, 2014). "We provide evidence for CCR2 expression on human FCs and a role for CCL2 in modulating FC migration towards the ASM bundle in asthma." (PMID 24931417, 2014).
asthma (continued). "In this study, analysis of the percentage of cells expressing CCR2 and CX3CR1 in the intermediate and non-classical monocyte subsets shows a strong inverse correlation, with CCR2 increased and CX3CR1 decreased, in patients with asthma compared to healthy controls." (PMID 31700522, 2019). "Our objective was to determine whether CD14, CD16, CCR2 and CX3CR1 on monocyte subsets are potential indicators of asthma severity." (PMID 31700522, 2019). "CX3CR1 expression was also lower, with a lower percentage of cells expressing CX3CR1 in the non-classical CD14+CD16++ subset in all patients with asthma and this was inversely related to the percentage of cells expressing CCR2." (PMID 31700522, 2019). "Analysis was done of the relationship between the genotypes defined by the combination of CCR5Δ32, CCR2-G190A, and CCR3-T51C polymorphisms in relation to asthma with or without atopy." (PMID 20220260, 2010). "The increase in CCR2 expression and decrease in CX3CR1 on CD16+ monocytes has not, to our knowledge, been described before in asthma and this association suggests a role for monocytes in asthma pathogenesis." (PMID 31700522, 2019). "This indicates that the lack of a requirement for CCR2 is not unique to a single asthma model." (PMID 15377395, 2004). "The percentage of monocytes expressing CCR2 in the intermediate CD14++CD16+ subset was significantly higher only in patients with mild (17 ± 4; p = 0.018) and moderate (17 ± 3; p = 0.003) asthma, not severe asthma, compared to healthy (7%) controls." (PMID 31700522, 2019). "The percentage of monocytes expressing CCR2 in the classical CD14++CD16− subset was not changed when patients with mild, moderate or severe asthma were compared with healthy controls." (PMID 31700522, 2019). "Thus these changes in CCR2 and CX3CR1 expression in intermediate and non-classical monocyte subsets indicate a more phagocytic phenotype and increased likelihood of endothelial damage adversely affecting asthma progression." (PMID 31700522, 2019).
fibrosis (23 papers, 2010 to 2025). the formation of excess fibrous connective tissue in an organ or tissue in a reparative or reactive process. "The recruitment of blood-borne fibrocytes implicated in tissue fibrosis is also CCR2 responsive and could theoretically play a role in the beneficial effects of CCR2 inhibition observed in our study." (PMID 25312642, 2014). "CCR2+ macrophage depletion markedly suppressed myocardial fibrosis, collagen deposition, and aberrant TGF-β/SMAD2/SMAD3 signaling activation in the hearts of DIC mice." (PMID 41208882, 2025). "Cell population source analysis and immunofluorescence labeling showed that the mouse fibrosis model contained highly expressing Ccr2 and Cd68 cell populations." (PMID 37724132, 2023). "We also demonstrated that the percentage of CCR2+ cells is significantly different in ET and PV patients with mild fibrosis (ET/PV-F) as compared to those evolved into spent phase (MF≥2)." (PMID 36072806, 2022). "In order to block monocyte migration into the infected tissues we administrated a CCR2 specific antagonist RS-504393, as was previously used in a fibrosis model." (PMID 29089636, 2017). "In bone marrow (BM) chimeric mice derived from CCR2-deficient mice, the study demonstrated the infiltration of CCR2+ BM-derived monocytes and fibroblasts into the colon, accompanied by an increased production of CCL2, which contributed to colonic fibrosis in BM chimeras." (PMID 40093318, 2025). "Tracking CCR2+ monocytes and macrophages in bleomycin- or radiation-induced fibrosis in mice and human samples of subjects with IPF (Clinical trial NCT03492762) indicates that PET uptake in the lung correlates with CCR2+ cell infiltration associated with fibrosis in mice." (PMID 39768150, 2024). "Clinical research has shown that CCR2+ (CCL2 receptor) macrophages and monocytes are extremely active in the lung and are located in the central area of fibrosis of IPF patients, indicating that CCL2/CCR2 plays an important role in the pathogenesis of fibrosis." (PMID 36556326, 2022). "Our further findings indicate that on the basis of the administration of CCR2/CCR5 dual inhibitor Cenicriviroc, further inhibiting MoMFs SYK may give patients with fibrosis additional benefits." (PMID 34853322, 2021). "CCR2 and CCR7 are proved to be expressed on HSCs and involved in cell migration, extracellular signal transduction, wound healing and fibrogenic responses in fibrosis models." (PMID 22905138, 2012). "However, pulmonary CCR2+ CD4+ T cells can attenuate PF progression, indicating that in fibrosis, variation in CCR2 expression could have different effects on different subsets of immune cells." (PMID 41472725, 2025). "Our observations are consistent with a study by Gurczynski and colleagues demonstrating no protection against ɣ-herpesvirus-induced pneumonitis and fibrosis with CCR2 KO mice and that CCR2+ cells played a suppressive role by limiting collagen and IL-17 production." (PMID 38594676, 2024). "Therefore, a strategy targeting CCR2/CCR5 may only be effective in early stages of NASH, but not in advanced fibrosis or cirrhosis." (PMID 37377968, 2023).
Hypertension (23 papers, 2012 to 2025). The presence of chronic increased pressure in the systemic arterial system. "Hypertension-induced infiltration of arterial wall macrophages was almost abolished and vascular hypertrophy was significantly decreased in CCR2-deficient mice." (PMID 36110847, 2022). "Based on these findings, therapeutic strategies targeting macrophages, such as inhibiting the CCR2 pathway to reduce macrophage recruitment, may help alleviate vascular remodeling and the pathological responses associated with hypertension." (PMID 40429668, 2025). "By interfering with CCR2, the EV-mediated propagation of hypertension could be mitigated, reducing BP and associated damage." (PMID 38539860, 2024). "Thus the CCR2:CCL2 axis is an important pathway during hypertension and associated vascular disease, and may be initially driven by infiltrating T cells leading to sequalae of pro-inflammatory events." (PMID 25501574, 2014). "Hydralazine also prevented angiotensin II-induced expression of Ccr2, and its ligands Ccl2 and Ccl8, consistent with Ccr2-mediated immune cell infiltration as a key aspect of brain inflammation during hypertension." (PMID 40697973, 2025). "CCR2 played a crucial role in macrophage infiltration, vascular hypertrophy, inflammation and remodeling in animal models of Ang II-induced hypertension." (PMID 36110847, 2022). "Going in line with this notion, development of hypertension was prevented in different models by blocking of macrophage activation using a CCR2 antagonist or macrophage depletion." (PMID 27091114, 2016). "Mice deficient in CCR2 exhibit decreased macrophage and monocyte infiltration into the arterial wall during Ang II-induced hypertension, suggesting that the CCR2:CCL2 axis is vital for leukocyte recruitment during hypertension." (PMID 25501574, 2014). "Clinical studies with colchicine, a blocker of the CCL2-CCR2 axis, have demonstrated the efficacy of anti-inflammatory treatment in preventing CVDs, reinforcing the need for further research on the role of the chemokine CCL2 and its receptor, CCR2, in conditions such as hypertension." (PMID 40859641, 2025). "An increase in the number of monocytes and neutrophils with the CXCL1 receptor CCR2 can be clearly detected in patients with hypertension, suggesting that blocking CCR2 may alleviate inflammation and control blood pressure." (PMID 36703963, 2022). "Consequently, a positive feedback loop of MCP-1 and CCR2 is formed and the influx of immune cells conduces to the recruitment of more inflammatory cells, driving organ injury and dysfunction by hypertension." (PMID 36195874, 2022). "At the same time, the CCR2 intensity on mononuclear cells is observed to be enhanced in the patients and rats with hypertension, suggesting that MCP-1 may regulate the functions of mononuclear cells through CCR2 and is related with vascular inflammation or AngII induced hypertension." (PMID 36195874, 2022). "Selective CCR2 receptor antagonist; demonstrated protective effect against hypertension in DOCA-salt animals, reducing CCR2 mRNA expression, reduces influx of M2 macrophages into the vessel wall and prevents arterial fibrosis." (PMID 40859641, 2025). "The literature mainly highlights the receptors CCR2, CCR5, CXCR1, CXCR2, and CXCR4 as the most relevant for the progression of hypertension." (PMID 40859641, 2025). "Blocking CCR2 and partially inhibiting CCL2 binding, as a plausible therapeutic target, could prove valuable in managing hypertension." (PMID 40859641, 2025). "Furthermore, experiments blocking CCR2, the receptor for both CCL2 and CCL12, demonstrated a reduction in BP in animal models of hypertension." (PMID 38539860, 2024). "However, in the progression of Ang II-mediated hypertension, locally produced CCL2 from endothelial cells binds CCR2+ on monocytes through an “inside-out” mechanism that promotes the migration of circulating monocytes to the tunica media." (PMID 39682749, 2024).
Hypertension (continued). "Accordingly, in response to hypertension or pressure overload, HSC and progenitor cells expand in the bone marrow and generate peripheral leukocytosis, with pro-inflammatory (Ly6C++CCR2+ in mice) monocytes infiltrating the heart in a CCR2-dependent manner." (PMID 31963368, 2020). "Moreover, the CCR2 antagonist INCB3344,7–9 reduces CCR2 expression and reverses macrophage accumulation in pVAT of mice with hypertension." (PMID 28838042, 2017). "Consistently, in two models of diastolic dysfunction, i.e. hypertension induced by salty drinking water with unilateral nephrectomy and chronic exposure to aldosterone (SAUNA) and physiological aging, cardiac macrophage expansion has been shown to rely on CCR2." (PMID 35090403, 2022).
Nephropathy (23 papers, 2005 to 2024). A nonspecific term referring to disease or damage of the kidneys. "In this review, MCP-1 had a very strong association with progression of renal disease, which is reinforced by preclinical studies showing that the blockade of MCP-1 receptor (CCR2) reduces interstitial fibrosis." (PMID 28219345, 2017). "Several studies have demonstrated that blocking of CCR2 has a therapeutic effect on kidney diseases." (PMID 31498850, 2019). "Conversely, the blockade of CCL2/CCR2 interaction by either neutralization of CCL2 or CCR2 antagonists has been shown to attenuate progressive kidney damage." (PMID 25807547, 2015). "In addition, our results go in line with published data from murine experimental approaches and suggest a protective interaction between CD73 and CCR2 in human kidney disease." (PMID 34299260, 2021). "Therefore, in this study, we demonstrated the therapeutic effect of CCR2 depletion on nephropathy in a HFD-induced obese animal model." (PMID 31498850, 2019). "CCL2/CCR2 signaling is believed to play an important role in kidney diseases." (PMID 31498850, 2019). "We employed two widely-used models of FSGS, the murine 5/6 nephrectomy remnant model and Adriamycin-induced nephropathy model, to test the hypothesis that blocking CCR2 would both reduce proteinuria and improve renal function." (PMID 29561839, 2018). "Interestingly, in our hands CCR2 deficient mice still exhibited significant renal disease and therefore CCR2 deficiency does not appear to improve renal function in our model of CKD." (PMID 35090403, 2022). "In the adriamycin-induced mouse model of nephropathy, researchers found that CCL2 in the kidney may recruit the infiltration of inflammatory and pro-fibrotic bone marrow-derived cell populations through its receptor CCR2; furthermore, a deficiency of Ccr2 in mice can ameliorate renal injury." (PMID 37908345, 2023). "The therapeutic impact of the blockade of CCR1, CCR2, CCR4, CCR5, or the corresponding ligands has been further studied in various renal disease models." (PMID 16200331, 2005). "By contrast, CCR2−/− mice were protected from cardiomyopathy, showed reduced mRNA expression of ECM genes and cardiomyocyte hypertrophy while still presenting kidney disease." (PMID 35090403, 2022). "Elevated CCR2 could increase the expression of multiple cytokines and chemokines, such as MCP-1, IL-6 and TNF alpha, and induces mesangial cell proliferation and matrix deposition, and further aggravate kidney damage." (PMID 35725391, 2022). "Ccr2 signalling mediates these kidney diseases by Agt, NFκB, Notch and Rela regulations." (PMID 31417109, 2019).